S100A9 (S100 calcium binding protein A9)
Diseases named in the same sentence as S100A9 in open-access papers (continued):
Sharing a sentence is not in itself a finding about the gene and the disease.
melanoma (continued). "High S100A9 levels in peripheral blood monocytes and a lower ratio of CD4+ T cells/monocyte was previously found to correlate positively with poor response to anti-PD-1 immunotherapy but inversely with overall survival in melanoma patients." (PMID 37347110, 2023). "To investigate the suitability of S100A9‐targeted VNPs to serve as a prophylactic immunotherapy preventing manifestation of lung metastasis, we used a lung metastasis mouse model using C57BL/6J mice i.v. challenged with B16F10 melanoma cells." (PMID 34519180, 2021). "Secretion of soluble factors such as VEGF-A, TNFα, and TGFβ from melanoma and lung cancer models has been previously demonstrated to induce the expression of inflammatory chemoattractants such as S100A8 and S100A9 in the premetastatic lungs, leading to myeloid cell recruitment." (PMID 33233625, 2020). "Interestingly, protein ligands S100A8 and S100A9 and cognate receptor TLR4 were all identified in melanoma EV cargo." (PMID 28424693, 2017). "Indeed, none of the melanoma experimental models tested reproduced S100A9 levels seen in a subgroup of patients with melanoma BM." (PMID 36652782, 2023). "Regarding the expression of genes associated with cellular processes, melanoma aggressiveness, resistance and cell survival, a significant difference was found in the expression of ABCB5, CAV1 and S100A9 compared with the control (cells not exposed to the extract)." (PMID 36431795, 2022). "In patients with primary melanoma, lung or breast adenocarcinoma developing brain metastasis, endogenous S100A9 levels in brain lesions correlated with clinical response to WBRT and underscored the potential of S100A9 levels in the blood as a noninvasive biomarker." (PMID 35411077, 2022). "Here, we expand upon this concept and demonstrate that multivalent display of S100A9‐targeting ligands directs the CPMV nanoparticles to the lung TME and induces treatment as evident by reduced tumor burden in the lungs after mice were i.v. challenged using melanoma cells or TNBCs." (PMID 34519180, 2021). "Dysregulation of S100a9 has been widely observed in many inflammatory conditions (such as IBD, arthritis, dermatitis, vasculitis, systemic sclerosis, infections, and cardiovascular diseases) and human tumors (colorectal, prostate, brain, lymphoma, melanoma, and thymus cancer)." (PMID 29326691, 2017). "By contrast, S100A7 shows a much wider expression pattern than S100A9, but despite its ability to promote cell proliferation, migration, invasion, and tumor metastasis in cervical, breast, and ovarian cancer, S100A7 has not previously been implicated in melanoma pathogenesis." (PMID 36139698, 2022). "In the majority of our melanoma cell lines, S100A9 expression could not be detected." (PMID 36139698, 2022). "Interestingly, S100A8 and S100A9 are not expressed by melanoma cells." (PMID 31806053, 2019). "Six targets—S100A9, FLG, SAMMSON, LY6D, CACNA2D2, and HES1—were found to have variable expression in different melanoma cell lines, so they could not be validated as GLI targets in melanoma." (PMID 36139698, 2022).
prostate carcinoma (35 papers, 2009 to 2025). A carcinoma that arises from epithelial cells of the prostate gland. "The amyloid protein S100A9, which is one of key factors promoting neuroinflammation, plays a role in prostate cancer invasion and is associated with disease progression." (PMID 36232958, 2022). "In line with this, we have previously shown that high density of S100A9 positive inflammatory cells in prostate cancer stroma is associated with poor outcome." (PMID 34067757, 2021). "Monocyte count and S100A9 levels are also associated with short prostate cancer-specific survival, with monocyte count providing independent prognostic information." (PMID 34067757, 2021). "S100A8/A9 are strongly up-regulated in breast, lung, gastric, colorectal, pancreatic, skin cancers and prostate cancer, in inflammation associated with cancer and altered S100A9 expression in carcinomas can lead to chemoresistance." (PMID 25298751, 2014). "S100A9 is a calcium binding protein that is said to have implications in cancer associated with inflammation, circM1D1 expression is highly upregulated in prostate cancer cells treated with MDSC exosomes and miR-506-3p was found to be an inhibitor of CRC progression through EZH2-targeted mechanisms." (PMID 41142789, 2025). "This is the first study showing that high blood monocyte count and high mRNA expression of S100A9 or S100A12 in PBMCs are associated with particularly poor outcome in patients with prostate cancer metastases, with monocytes providing independent prognostic information." (PMID 34067757, 2021). "When we shift the focus to MDSCs-derived exosomes derived in the TME, it was observed that these exosomes promoted the development of castration-resistant prostate cancer by upregulating the S100A9/circM1D1/miR-506-3p axis." (PMID 41142789, 2025). "Recently, an inhibitor of S100A9 was used in clinical trials as a therapy for prostate cancer and other solid tumors." (PMID 35042454, 2022). "S100A9 and a high monocyte count were associated with increased relative risk for both PSA progression and prostate cancer-specific death." (PMID 34067757, 2021). "A previous study analyzing circulating S100A9 protein levels in serum showed higher levels of S100A9 in prostate cancer patients compared to healthy men." (PMID 34067757, 2021). "High protein and mRNA expression of S100A9 are also reported for prostate cancer tissue compared to surrounding benign tissue, and in high-grade compared to low-grade cancers." (PMID 34067757, 2021). "Taken together, this shows that high levels of S100A9, S100A12 and high monocyte count in blood are associated with a particularly bad outcome in patients with prostate cancer metastases." (PMID 34067757, 2021). "S100A8 and S100A9 expression levels increased in several types of cancer, including gastric, colon, pancreatic, bladder, ovarian, thyroid, breast, skin and prostate cancer." (PMID 25673070, 2015). "For example, phorbol esters stimulate secretion of S100A8/A9 by prostate cancer cells and S100A9 expression is induced in hepatocellular carcinoma through activation of NF-KB signaling." (PMID 25298751, 2014). "Recently, S100A8 and S100A9 were identified in amyloid aggregates in corpora amylacea of prostate cancer patients." (PMID 23483999, 2013). "For example, in a study that proposed that serum S100A9 would serve as a useful marker to discriminate between prostate cancer and benign prostatic hyperplasia, the serum S100A9 concentration measured by ELISA was about 2–14 ng/mL in cancer patients." (PMID 22685372, 2012). "We conclude from these preliminary data that S100A9 expression is up-regulated in prostate cancer tissue compared to adjacent normal prostate and that this expression seems to correlate with infiltrating macrophage-like cells." (PMID 22470535, 2012).
prostate carcinoma (continued). "The list of up and downregulated genes in VEGFA165 tumours include known genes involved in neoplasia (e.g. S100A8 involved in leukaemia; S100A9 in prostate carcinoma; BCL9, CCND1 and CTNNB1)." (PMID 22045186, 2011). "In particular, the enhanced secretion of S100A8 and S100A9 was found in human prostate cancer cells." (PMID 19440546, 2009). "Tasq is a drug designed initially to target hormone-resistant advanced prostate cancer and may have notable potential as a new clinical drug for the treatment of AP due to its specific inhibition of S100A9." (PMID 41001098, 2025). "Also, it has been shown that high numbers of S100A9+ inflammatory cells in tumor stroma correlated with shorter survival in patients with prostate cancer." (PMID 37347110, 2023). "Several S100 proteins, including S100A9, have received attention regarding their possible role in tumor development and progression and studies report an increased expression in a variety of tumors, including ovarian, colon, gastric, and prostate cancer." (PMID 37016361, 2023). "The S100A9 inhibitor tasquinimod already demonstrated both efficacy and a favorable toxicity profile in castrate-resistant prostate cancer (NCT01732549, NCT01234311) and might offer an alternative and safer approach to disturb the cancer cell metabolism." (PMID 38110349, 2023). "Thus, the results showed that MDSC-Exo promoted prostate cancer cell migration, proliferation, and invasion through S100A9/circMID1/miR-506-3p/MID1 signaling." (PMID 35918733, 2022). "Evidence has demonstrated that S100A9 is elevated in various solid tumors and that the upregulation of S100A9 positively correlates with poor outcomes in colorectal, gastric, liver, pancreatic and prostate cancer." (PMID 34157683, 2021). "Taken together, our results suggest that analysis of monocytes or expression levels of S100A9 or S10012 in a blood sample could provide additive prognostic information for prostate cancer patients with metastases at diagnosis." (PMID 34067757, 2021). "However, prostate cancer cells and other cells, such as neutrophils and mast cells, have also been shown to express S100A9." (PMID 34067757, 2021). "Moreover, the presence of circulating S100A9 has been suggested as a marker to distinguish prostate cancer from benign prostate enlargement." (PMID 24162378, 2014). "Also, an increase in HIF-1α protein induced by hypoxia enhances transcription, expression, and secretion of S100A9 protein in the tumor microenvironment also by prostate cancer cells." (PMID 25193858, 2014). "Amyloid aggregates of the calcium-binding EF-hand proteins, S100A8 and S100A9, have been found in the corpora amylacea of patients with prostate cancer and may play a role in carcinogenesis." (PMID 23483999, 2013). "We wanted to address whether S100A9 expression could influence the growth of a solid cancer in a spontaneous prostate cancer model." (PMID 22470535, 2012). "In sections from human prostate cancer biopsies, many immune cells in the stroma could be seen to express S100A9 and the number of CD68+ macrophages correlated with the number of S100A9+ foci." (PMID 22470535, 2012). "By using multidisciplinary analysis of corpora amylacea inclusions in prostate glands of patients diagnosed with prostate cancer we have revealed that their major components are the amyloid forms of S100A8 and S100A9 proteins associated with numerous inflammatory conditions and types of cancer." (PMID 19440546, 2009). "Numerous prior investigations have demonstrated that the expression level of S100A9 in PCa tissues is significantly lower than that in benign prostatic hyperplasia tissues, thereby implying that the S100A9 protein serves as a suppressor of prostate cancer progression." (PMID 41169378, 2025).
prostate carcinoma (continued). "Another study showed contradictive results and could not detect any difference in plasma levels of S100A9 between prostate cancer patients with different risk profiles and controls, thus confirming the need for further evaluation." (PMID 34067757, 2021). "Similarly, the expression of S100A9 is increased early in the course of prostate cancer and may contribute to tumour development and metastasis." (PMID 24162378, 2014). "We next wanted to verify that S100A9 expression could also be detected in human prostate cancers." (PMID 22470535, 2012). "The aim of this prospective study was to assess the prognostic value of the inflammation markers S100A9 and S100A12 together with the monocyte count in blood samples from a cohort of 121 prostate cancer patients." (PMID 34067757, 2021). "More studies are needed to understand the mechanisms behind as well as the effects of the increased levels seen for circulating monocytes and expression of S100A9 and S100A12 in PBMCs in prostate cancer patients with particularly poor prognosis." (PMID 34067757, 2021). "In this prospective study, we evaluated the mRNA levels of two members of this family, S100A9 and S100A12, in peripheral blood mononuclear cells (PBMCs) in a cohort of 121 prostate cancer patients using RT-PCR." (PMID 34067757, 2021). "In this prospective study, the aim was to evaluate the level distribution of S100A9 and S100A12 in peripheral blood mononuclear cells (PBMCs) and its prognostic value in prostate cancer patients." (PMID 34067757, 2021). "We here report our findings concerning the role of S100A9 and TLR4 expression using the spontaneous prostate cancer model TRAMP, as well as the transplanted, syngeneic EL4 lymphoma model." (PMID 22470535, 2012). "We have shown here that the absence of S100A9 or TLR4 expression delays tumor incidence in a spontaneous prostate cancer model." (PMID 22470535, 2012). "Moreover, the absence of S100A9 or TLR4 expression delays tumor incidence in a spontaneous prostate cancer model." (PMID 26315114, 2015). "We did not confirm if the levels of S100A9, S100A12 and monocytes in blood reflected an inflammatory profile in the prostate cancer tissue, but this is not unlikely." (PMID 34067757, 2021). "The importance of these interactions in tumour development was illustrated in experiments in knock-out mice showing that in the absence of S100A9 or TLR4, the development of spontaneous prostate cancer tumours was delayed." (PMID 24162378, 2014). "However, the decrease in S100A9 levels after ADT treatment was not correlated with PFS (r = −0.099, p = 0.646) or prostate cancer-specific death (r = −0.082, p = 0.704)." (PMID 34067757, 2021).
colitis (34 papers, 2012 to 2025). Inflammation of the colon. "Although S100A9 is pro-apoptotic at high concentration, it is required for colitis-associated cancer development." (PMID 34572138, 2021). "We observed the regulatory effects of exosomal S100A9 from G‐MDSCs on CRC cell stemness in a murine colitis‐associated colon cancer (CAC) model." (PMID 31559140, 2019). "We previously revealed that S100a8 and S100a9 are highly activated and play an important role in the process of colitis-associated carcinogenesis, which suggests an attractive therapeutic target for ulcerative colitis and related colon cancer." (PMID 29326691, 2017). "We and others also revealed that S100a9 was upregulated in virtually all steps of colitis-associated tumorigenesis." (PMID 29326691, 2017). "Injection of anti-S100a9 Ab or infliximab (anti-TNFα Ab) during colitis induction significantly ameliorated body weight loss and DAI scores compared with that of injection of control IgG Ab." (PMID 29326691, 2017). "Increased expression of S100A9 was observed in colitis-associated colon cancer, gastric cancer and lung cancer." (PMID 27021626, 2016). "Like CHI3L1, the damage-associated molecular (DAMP) protein S100A9 is also usually undetectable in healthy colons, but can be induced in colonic mucosa during colitis." (PMID 26431492, 2015). "Furthermore, our results demonstrate that the expression of genes related to the pathogenesis and diagnosis of colitis such as Il1β, Lcn2, S100a8 and S100a9 were specifically enhanced in Socs3-deficient neutrophils localized to the colon and spleen." (PMID 37283760, 2023). "This interaction disrupts the S100A9-associated expression positive feedback loop during early immune activation, creating a CHI3L1hi S100A9low colonic environment, especially in the later phase of colitis, which promotes cell proliferation/survival of both normal IECs and tumor cells." (PMID 26431492, 2015). "Functional profiling revealed that human S100A8 and S100A9 homodimers enhanced activation of cluster of differentiation 4+ and 8+ T cells, which promoted experimental colitis." (PMID 41295942, 2025). "The observation that Fh15 treatment significantly reduced the levels of CHI3L1 and S100A9 is, therefore, consistent with the substantial reduction in the number of neutrophils and macrophages in the colonic tissue of colitis mice." (PMID 40497975, 2025). "Consistent with previous work, in the DSS mouse model, the expression levels of Cd44, S100a8, S100a9 and Timp1 were greater in the mice with colitis; while the expression level of Ndrg1 was lower in the mice with colitis." (PMID 38778086, 2024). "The gut mucosal DAMPs S100A8 and S100A9 have recently come to be recognized as pivotal agents in the pathogenesis of colonic inflammation." (PMID 38892354, 2024). "Histochemical results showed that the expression of S100a9 in intestinal tissue of colitis mice was increased, and it was positively correlated with neutrophils and macrophages." (PMID 38448514, 2024). "In our animal model, S100a9 mRNA and protein levels were significantly elevated in mice with colitis." (PMID 38448514, 2024). "Inhibition of S100a9 expression significantly reduced intestinal immune cell infiltration and inflammatory response in mice with colitis." (PMID 38448514, 2024). "Specifically, in TNBS-induced colitis, Cd44, Numa1, S100a8, S100a9, Timp1 and Xbp1 were more highly expressed, while Cidec and Rag1 were less expressed." (PMID 38778086, 2024). "The mRNA expression levels of Cxcr2, Chi3l1 and S100a9 in colitis mice were significantly higher than those in control group, especially S100a9, which was consistent with our bioinformatics analysis results." (PMID 38448514, 2024). "Consistent with the results of the qPCR experiment, the S100a9 protein was overexpressed in the intestinal tissue of colitis mice." (PMID 38448514, 2024).